SIRT1 (sirtuin 1)
Diseases named in the same sentence as SIRT1 in open-access papers (continued):
Sharing a sentence is not in itself a finding about the gene and the disease.
breast cancer (continued). "However, the underlying molecular mechanism by which SIRT1 regulates H3 and H4 acetylated marks, and consequently cancer-related gene expression in breast cancer, remains uncharacterized." (PMID 30093977, 2018). "Furthermore, studies have shown that SIRT1 deficiency promotes or suppresses tumors in breast cancer, making it an attractive therapeutic target in cancer treatment." (PMID 30380732, 2018). "Genotype distribution and allele frequency of SIRT1 variants in control and breast cancer groups." (PMID 26999517, 2016). "Our study is the first to report an association of SIRT1 gene polymorphism, namely rs3758391 and rs12778366, and, to a lesser extent rs3740051, with breast cancer risk, with the T allele (for rs3758391 and rs12778366) and the G allele (for rs3740051) being potential risk factors." (PMID 26999517, 2016). "Summarizing all these data, one may assume that human SIRT1 expression and SIRT1 genetic variants may play a role in breast cancer clinicopathological features together with disease progression." (PMID 26999517, 2016). "Association of SIRT1 rs3740051 gene polymorphism with breast cancer clinicopathological variables." (PMID 26999517, 2016). "In the current investigation, a highly significant association was observed between SIRT1 rs12778366 and breast cancer as evidenced by significantly higher TT genotype distribution and T allele frequency in breast cancer patients compared to normal control subjects." (PMID 26999517, 2016). "Association of SIRT1 rs3758391 gene polymorphism with breast cancer clinicopathological variables." (PMID 26999517, 2016). "Actually, previous reports linked ER and PR status to expression of SIRT1 in breast cancer tissue." (PMID 26999517, 2016). "Association of SIRT1 rs12778366 gene polymorphism with breast cancer clinicopathological variables." (PMID 26999517, 2016). "In the present study, both SIRT1 SNPs rs3758391 and rs12778366 were associated with histologic grade and lymph node invasion in breast cancer patients, as manifested by significantly higher frequencies of the TT genotype with higher tumor grades and higher lymph node involvement." (PMID 26999517, 2016). "Recently, SIRT1 was found to be highly expressed in various cancers, and high levels of SIRT1 expression were shown to be associated with a poor prognosis in lung cancer, breast cancer, B-cell lymphoma, and gastric carcinomas." (PMID 27528025, 2016). "Indeed, a decreased SIRT1 level in breast cancer is associated with BRCA1 mutations, suggesting it as a tumor suppressor." (PMID 27916001, 2016). "Concerning SIRT1 SNP rs3758391, a highly significant statistical difference was observed in the T allele frequency and TT genotype distribution between the normal control and breast cancer groups (p < 0.0001)." (PMID 26999517, 2016). "However, a significant decrease in SIRT1 expression is observed in breast cancer 1-associated breast cancer than in normal controls." (PMID 25522783, 2014). "Additionally, SIRT1 is highly expressed in various cancers such as prostate cancer, and high levels of SIRT1 expression are associated with a poor prognosis in lung cancer, breast cancer, gastric carcinomas, and B-cell lymphoma." (PMID 25424420, 2014). "Interestingly, sirtinol decreases the expression of SIRT1 in MCF-7 breast cancer cells, causing cell cycle arrest in the G1 phase and apoptotic cell death, while inducing caspase-independent autophagic cell death in MCF-7 cells." (PMID 25486244, 2014). "SIRT1 expression is decreased in breast cancer arising in BRCA1 mutation carriers." (PMID 24278473, 2013). "To assess the effect of SIRT1 on the emergence and progression of mammary tumors, we crossed mice that harbor a point mutation that abolishes SIRT1 catalytic activity with mice carrying the polyoma middle T transgene driven by the murine mammary tumor virus promoter (MMTV-PyMT)." (PMID 24278473, 2013).
breast cancer (continued). "Moreover, recent reports have shown that the expression of SIRT1 is associated with a poor prognosis in specific human tumors including hepatocellular carcinoma, gastric cancer, breast cancer, and diffuse large B cell lymphoma." (PMID 23024800, 2012). "This suggests that if SirT1 serves as a lifetime sensor to dietary restriction and acute withdrawal of nutrients, its activity could ultimately influence the risk of breast cancer." (PMID 17201918, 2007). "Also, their data implicate that SIRT1 rs3740051 can be a possible contributor to breast tumorigenesis and suggest that the G allele may play a role in the increased expression of SIRT1 and higher susceptibility to breast cancer." (PMID 31747893, 2019). "However, the underlying molecular mechanism by which HDAC SIRT1 regulates its acetylated histone targets, and consequently cancer-related gene expression in breast cancer, is still unknown." (PMID 30093977, 2018). "We, therefore, conducted the present study to investigate SIRT1 genetic variants in a series of breast cancer cases as well as controls to determine whether SIRT1 polymorphism influences the risk for the development of breast cancer and prognosis." (PMID 26999517, 2016). "For example, SIRT1 expression was found to be significantly associated with shorter overall and relapse-free survival of gastric carcinoma, distant metastatic relapse and shorter survival in breast carcinoma and overall survival and event-free survival in soft tissue sarcoma." (PMID 25569080, 2015). "Thus, reduction of survivin via SIRT1 activity may play an important role in BRCA1-associated mammary tumor formation." (PMID 25486244, 2014). "SIRT1 is often overexpressed in various cancer types, including colorectal cancer and breast cancer, suggesting its role as a strong oncogenic driver." (PMID 40855785, 2026). "Serum SIRT1 levels are significantly elevated in breast cancer compared to benign fibroadenoma cases and healthy controls, indicating its potential as a diagnostic biomarker." (PMID 41471349, 2025). "In some breast cancer cells, SIRT1 deacetylates NF-κB (p65) at K310, thereby suppressing the transcription of pro-inflammatory and pro-senescent genes, such as IL-6 and IL-8." (PMID 41008982, 2025). "SIRT1 was also demonstrated to promote breast cancer formation by interacting with and promoting the activity of AKT." (PMID 40165290, 2025). "SIRT1 contributes to breast cancer by promoting several pathways that are crucial for cancer cell survival and proliferation." (PMID 41436543, 2025). "SIRT1 plays multifaceted role in breast cancer including, its role in cell proliferation and survival, metabolic reprogramming, and drug resistance." (PMID 41436543, 2025). "In Saudi breast cancer patients, high nuclear SIRT1 correlated with lymph node metastasis and poor disease-specific survival in HER2+ tumors, while cytoplasmic SIRT1 had opposing effects." (PMID 41471349, 2025). "Neutrophils promote breast cancer lung metastasis through the SIRT1-Naged-NETs axis in breast cancer." (PMID 40564191, 2025). "pursued this further by screening selisistat, a selective SIRT1 inhibitor, with paclitaxel in models of breast cancer." (PMID 41425553, 2025). "Reduced expression of Sirtuin 1 (SIRT1) inhibits lysosomal function, promoting breast cancer aggressiveness and survival." (PMID 40781072, 2025). "In summary, SIRT1 plays a complex role in HER2+ breast cancer, with evidence pointing to both tumor-suppressive and oncogenic functions depending on the context." (PMID 41300302, 2025). "For instance, CR mimetics have been shown to decrease breast-cancer-stem-cell-marker-expressing cells in a SIRT1-dependent manner in the MDA-MB231 breast cancer model." (PMID 39940361, 2025). "Experimental evidence has demonstrated that increased DBC1 expression markedly diminishes the tumor-suppressive effects of SIRT1 in breast cancer, significantly shortening the survival of both ERα-positive and ERα-negative patients." (PMID 40692869, 2025).
breast cancer (continued). "The authors further demonstrated that the knockdown of SIRT1 expression decreases the viability and colony formation of MCF-7 breast cancer cells, thus suggesting SIRT1 as a cell survival factor in breast cancer." (PMID 40214422, 2025). "SIRT1 is significantly overexpressed in HER2-enriched breast cancer subtypes compared to normal tissues." (PMID 41300302, 2025). "In a recent study, it was shown that resveratrol reverses the EMT properties of MCF-7/ADR (multi drug resistant breast cancer cells) by regulating the connection between SIRT1 and β-catenin pathway." (PMID 40001961, 2025). "have demonstrated that in breast cancer, SIRT1 enhances NRF2 translocation and GSH generation, thereby reinforcing doxorubicin resistance, tumor angiogenesis, and metastasis." (PMID 41425553, 2025). "Collectively, these findings indicate that SIRT1 is a key regulator of redox adaptation and senescence evasion in breast cancer." (PMID 41008982, 2025). "Another study observed that SIRT1 expression is reduced in TNBC, and its loss alters the secretome of breast cancer cells, potentially influencing tumor behavior." (PMID 41300302, 2025). "Cancer Stem Cell Properties: Inhibition of SIRT1 has been shown to reduce cancer stem cell populations and block EMT in breast cancer cells, indicating that SIRT1 contributes to the maintenance of stem-like properties and metastatic potential in TNBC." (PMID 41300302, 2025). "In breast cancer, SIRT1 can act both as a promoter and a depressor of cancer progression, depending on the context of its expression and the cellular environment." (PMID 41300302, 2025). "In summary, this study suggests that the herbal recipe SLC has the potential to act as an agent for inhibiting OXPHOS through the PDK1/PDHA1 and SIRT1/PGC-1α/NRF1/TFAM signaling axis to treat HER2-positive breast cancer." (PMID 41465397, 2025). "Notwithstanding, recent studies have supported the breast cancer-promoting effects of SIRT1 and SIRT6." (PMID 40214422, 2025). "In breast cancer models, nicotinamide has shown promising results in overcoming drug resistance by disrupting the SIRT1/Akt signaling pathway." (PMID 41008982, 2025). "In HER2+ breast cancer cells, SIRT1 expression is induced by 17-β-estradiol through the G-protein-coupled estrogen receptor (GPER)." (PMID 41300302, 2025). "In HER2+ breast cancer cells, SIRT1, along with SIRT6, has been shown to modulate the acetylation status of the transcription factor FOXO3, thereby influencing sensitivity to lapatinib, another HER2-targeted therapy." (PMID 41300302, 2025). "In breast cancer, SIRT1 promotes tumor progression by enhancing redox adaptation and suppressing senescence." (PMID 41008982, 2025). "Silencing GPER or SIRT1, or introducing the SIRT1 inhibitor Sirtinol, abolishes these effects, suggesting the importance of the SIRT1-GPER axis in HER2+ breast cancer progression." (PMID 41300302, 2025). "SIRT1 is frequently overexpressed in breast cancer, particularly in patients with metastatic disease." (PMID 41471349, 2025). "Like its activity in HER2+ breast cancer, SIRT1 exhibits complex and context-dependent roles in TNBC." (PMID 41300302, 2025). "This study examines how SIRT1 protein levels correlate with clinicopathological characteristics and survival outcomes in patients with breast cancer." (PMID 39858444, 2025). "MDSCs-derived exosomal miR-155-5p promotes the migration and invasion of HR + breast cancer cells by targeting SIRT1." (PMID 41281644, 2025).
breast cancer (continued). "Further investigation of MDSC-mediated regulation of SIRT1 expression in breast cancer tissues from the TCGA BC cohort revealed that SIRT1 was downregulated in the MDSCshigh group." (PMID 41281644, 2025). "Recent research studies showed that PTS-catechol appears to contribute stronger biological activities than PTS in human breast cancer cells, and possesses anti-adipogenic, anti-inflammatory, anti-oxidant, and sirtuin 1 (Sirt-1) inhibitory activities." (PMID 39337478, 2024). "Nitrosative stress can also induce autophagy in breast cancer by upregulating SIRT1 and its interaction with AMPK." (PMID 39403142, 2024). "SIRT1 is a member of the sirtuin family of proteins, which have been extensively studied in multiple cancers, including breast cancer." (PMID 38611028, 2024). "NNMT was also reported to regulate the expression/activity of SIRT1 in prostate and breast cancer cells by supporting SIRT1 stabilization." (PMID 38396769, 2024). "Doxorubicin-induced SIRT1 promotes redox imbalance and chemoresistance in breast cancer by enhancing cell proliferation, angiogenesis, and metastasis through NRF2 activation and increased glutathione levels." (PMID 39403142, 2024). "Low SIRT1 expression in breast cancer cells and podocytes in diabetic nephropathy is associated with impaired lysosomal function and increased secretion of pathogenic exosome cargo, aggravating pathology." (PMID 39596439, 2024). "SIRT1 inhibits EMT in HMLER breast cancer cells by deacetylating Smad4 and preventing TGF-β signaling." (PMID 39479446, 2024). "Resveratrol inhibits neutrophil extracellular trap formation by targeting SIRT1, thereby reducing breast cancer metastasis and promoting CD8+ T cell infiltration in a murine model." (PMID 39403142, 2024). "Previous studies have identified miR-22 as an important regulator in inhibiting tumorigenesis and enhancing radiosensitivity of breast cancer cells by targeting sirtuin 1 (SIRT1)." (PMID 38807590, 2024). "SIRT1 has been extensively examined in CSCs, as in normal cells, with a particular emphasis on its high expression in glioma, breast cancer, colorectal cancer, and leukemia." (PMID 38397988, 2024). "For instance, targeting HDAC1 can impact SIRT1’s function, potentially offering a novel therapeutic approach for treating breast cancer." (PMID 39456765, 2024). "In breast cancer and colorectal cancer, there has been reported to be a connection between SIRT1 expression and lymph node metastasis." (PMID 39403142, 2024). "In conclusion, our findings demonstrate that Neratinib promotes cell senescence of mammary cancer cells by inducing DNA damage and reducing telomerase activity mediated by inhibition of SIRT1." (PMID 38829772, 2024). "In line with this, melanoma also exhibited the largest concentration of IL-1β, TNFα, and Sirtuin-1, which was followed by the concentration determined in mammary carcinoma homogenates." (PMID 38698774, 2024). "In breast cancer, the mechanisms of SIRT1 in chemoresistance, particularly its role in amplifying MDR1 gene expression and mediating drug resistance, need further exploration." (PMID 38203666, 2023). "miR-34a plays an inhibitory role by targeting Bcl-2 and SIRT1 and down-regulating their expression in breast cancer." (PMID 37333450, 2023). "Results have displayed that SIRT1 is significantly up-regulated in breast cancer tissues and cells, which is correlated with histological grade, tumor size, and lymph node metastasis." (PMID 38081857, 2023). "The consistent SIRT1 cellular expression pattern, identified in our malignant tumor samples and characterized by relative loss and cytoplasmic shift, allows us to hypothesize that SIRT1 may be a tumor modulator and may even play an onco-suppressive role in canine mammary tumors." (PMID 37627400, 2023). "These interactions between estrogen receptors and SIRT1 explain the relationship between estradiol and the cellular lifespan, at least in cancer breast cancer cells." (PMID 37762053, 2023).
breast cancer (continued). "Sirt1 also plays a confirmed role in some tumor cells, such as ovarian, thyroid, pancreatic cancers, and breast cancer; meanwhile, Sirt1 can serve as useful biomarkers for predicting WEE1 inhibitor sensitivity or resistance." (PMID 37190639, 2023). "NNMT overexpression increases the chemoresistance through SIRT1 stabilization and activity in breast cancer." (PMID 36817086, 2023). "Several canine mammary tumor cells were analyzed to determine the endogenous levels of SIRT1 by Western blot analysis." (PMID 37627400, 2023). "As a transcription factor, ERα binds to the promoter of Sirt1 and increases Sirt1 expression in breast cancer cell line." (PMID 36942499, 2023). "Thus, breast cancer tumorigenesis and survival may be hampered by SIRT1 blockage while the enhancement of SIRT1 expression caused by estradiol may act inversely if the results obtained in the ZR75.1 breast cancer cell line can be extrapolated to other cell lines and in vivo tumors." (PMID 37762053, 2023). "The roles of SIRT1 in breast cancer is multifaceted depending on its substrate from upstream or downstream signaling pathway." (PMID 38081857, 2023). "We, therefore, aimed to study possible SIRT1 involvement in different types of canine spontaneous mammary tumors (CMTs) and in different cultured CMT cell lines, employing a model previously published." (PMID 37627400, 2023). "We have also demonstrated that SIRT-1 activation is essentially required for fatty acid metabolic reprogramming and apoptosis induction by adiponectin in breast cancer cells." (PMID 34986886, 2022). "For example, in MDA-MB-231 breast cancer cell line, SIRT1 reduced the inhibitory effect exerted by DNMT1 on tumor suppressor genes ERα and CDH1." (PMID 35215560, 2022). "Sirtuin-1 (SIRT-1) cooperates with estrogen signaling in breast cancer tumorigenesis and progression." (PMID 35563441, 2022). "Supporting this, the downregulation of SIRT4 in breast cancer cell lines resulted in decreased expression of SIRT1 and stem cell markers Oct4, Sox2, and Nanog." (PMID 36291902, 2022). "We next challenged MCF-7 clones with SRT1720, a synthetic compound activating SIRT1 and known to activate autophagy and enhance lysosomal membrane permeabilization, a process leading to the death of breast cancer cells." (PMID 35351824, 2022). "It has been revealed that SIRT1 is significantly up-regulated in invasive ductal breast carcinoma relative to normal tissue, further suggesting a role of SIRT1 in breast cancer development and progression." (PMID 35900723, 2022). "This needs to be investigated further, considering that SIRT1 is constitutively upregulated in breast cancer and its inhibition suppresses breast cancer (as discussed in 2.1 above)." (PMID 36291902, 2022). "A similar observation was made after the application of DBC1 (deleted in breast cancer-1), SIRT1′s negative regulator." (PMID 36499440, 2022). "Given the previous findings that altered lipid metabolism critically contributes to the induction of breast cancer cell death by adiponectin, subsequent experiments were designed to determine the implication of SIRT-1 in the modulation of cancer cell fate." (PMID 34986886, 2022). "The authors concluded that the negative regulation of SIRT1 by miR-211-5p reduces survival and induces cell death of breast cancer." (PMID 36291902, 2022).